FOXP3 (forkhead box P3)
Diseases named in the same sentence as FOXP3 in open-access papers (continued):
Sharing a sentence is not in itself a finding about the gene and the disease.
tumor (continued). "IHC staining indicated that FOXP3 + Tregs mostly accumulated in the invasive fronts of OSCC tissues but were sporadically distributed throughout the tumor." (PMID 38515216, 2024). "A systematic review showed that the levels of FoxP3+ tumour-infiltrating lymphocytes in patients with HNSCC were positively correlated with patient survival prognosis." (PMID 39678507, 2024). "Considering that one of the most important functions of Tregs is to suppress other immune cells, the high CD8+/FOXP3+ ratio denotes an escape of tumor cells from the immune surveillance." (PMID 38474377, 2024). "FOXP3 expressing regulatory T cells (Tregs) can suppress autoimmune response but also affect anti-tumor immunity." (PMID 38167862, 2024). "Next, we assessed the anti-inflammatory T cells in the tumor microenvironment by quantifying FoxP3(+) regulatory T cells (Tregs)." (PMID 38895115, 2024). "These populations include CD66b+ tumor-associated neutrophils (TANs), FoxP3+ Tregs, and CD163+ tumor-associated macrophages (AMs)." (PMID 38730579, 2024). "An analysis of the tumour-immune phenotype revealed a significant association between PD-L1 expression and IL17+CD4+ and Foxp3+CD4+ immune phenotypes." (PMID 39409156, 2024). "Knockdown of the NR4A genes in intratumor Tregs attenuates Treg activity with the decrease of Foxp3 and CTLA-4 and develops effective T helper cell (Th) 1 and CTLs-associated anti-tumor immunity." (PMID 39227959, 2024). "rAd5-16/E6E7Wt with or without the anti-PD-1 checkpoint inhibitor induced a significant increase in the number of CD4+ and CD8+ T cells in the tumor mass along with an increase in Treg cells (defined as CD45 + CD3 + CD4 + FoxP3+)." (PMID 39339987, 2024). "mIF on FFPE samples with antibodies of CD4, CD8α, FOXP3, Granzyme B, and pan CK were applied to analyze the tumor regions of pre- and post-ipilimumab treatment for 4 patients (P6, P7, P4 and P8)." (PMID 38448521, 2024). "Foxp3+Treg benefits from changes in tumor glycolysis because it strengthens its immunosuppressive capacity in the tumor microenvironment and encourages tumor cell survival." (PMID 38919615, 2024). "Third, Foxp3 forms complexes with Ets1 and AP-1 proteins, such as Batf that is highly expressed in tumor-infiltrating Treg cells." (PMID 39882241, 2024). "NEW & NOTEWORTHY In this study, we revealed a novel c-FOXP3+ tumor epithelial cell subset marked by diminished E-cadherin and stable FOXP3 expression." (PMID 38047300, 2024). "Regulatory T cells (Tregs), constituting 5–7% of CD4+ T cells, predominantly express FOXP3, repressing anti-tumor immunity and promoting tumor growth." (PMID 39614322, 2024). "Phenotypic analyses of tumor-infiltrating cells revealed significantly lower percentages of PD-1+ (p = 0.009) and FoxP3+ (p = 0.028), and a higher percentage of NKp46+ (p = 0.011) CD3+CD49+ cells in the metformin-treated group." (PMID 38892058, 2024). "Evidence suggests an increase in Foxp3 expression and suppressive activity of Tregs in inflammatory and transplantable tumor models." (PMID 39690423, 2024). "The immunophenotyping of tumor-infiltrated immune cells showed lower levels of Foxp3+ Tregs in the group that received combination therapy compared with the groups that received each of these therapies independently." (PMID 39247196, 2024). "Differential gene expression results revealed five genes (IDO1, IL6, TNF, CD209, and FOXP3) that were, on average, upregulated ≥ 2-fold or downregulated ≤ –2-fold in treated tumor regions relative to untreated tumor regions." (PMID 39335552, 2024). "Tumor derived TGFβ plays an important role in this promotion of FoxP3 expressing Tregs from naïve CD4+ T cells." (PMID 38571964, 2024). "The ratio between different subgroups of T-cells thus provides an informative measure for tumor occurrence and progression, for example, the CD8+/CD4+ and CD8+/FOXP3+ ratios are the most-used measurement for the potency of anti-tumor immune activity." (PMID 38474377, 2024).
tumor (continued). "We also observed that CD3+CD8+GrB+ T cells were relatively close to tumor cells compared to CD3+FoxP3+ and CD3+FoxP3+Ki67+ T cells, with median distances of 33.9, 54.6, and 86.6 μm, respectively." (PMID 38375478, 2024). "To determine the role of Foxp3+ Tregs in Zn-mediated regulation of tumor immunity, we used FOXP3-GFP-DTR mice." (PMID 39247196, 2024). "First, in a cohort of early‐stage LUAD patients from HGUV we found that those patients with high FOXP3+ infiltration in tumor had high expression of LGALS3 in tumor." (PMID 37567864, 2024). "Treatment with cps is also accompanied by accumulating some splenocytes, including macrophages, B cells, NK cells, and CD4+ T cells, and decreasing the number of Foxp3+ CD4+ T regulatory cells in the tumor microenvironment." (PMID 38109851, 2024). "CCR4 is a chemokine receptor for the metastatic process of Tregs and in tumor-infiltrating Foxp3+ Treg populations, most of which express CCR4." (PMID 39329710, 2024). "In vivo results show that IFI27 inhibits the Treg cell-specific marker FOXP3, thereby hindering Treg cell recruitment to the tumor and immune organs." (PMID 39668835, 2024). "Analyses of the cellular make up of tumor-infiltrating leukocytes detected a reduced percentage of FoxP3+ (p = 0.001) CD4+CD25+ cells and IL-10+ (p = 0.0001) CD4+CD25+FoxP3+ cells in metformin-treated mice compared to the non-treated group." (PMID 38892058, 2024). "The combination of CCKR blockade results in a significant decrease in tumor FOXP3+ Tregs and an increase in CD4+ and CD8+ lymphocytes." (PMID 37529035, 2023). "FOXP3-expressing regulatory T (Treg) cells eliminate aberrant immune response including anti-tumor immune response." (PMID 37415251, 2023). "The authors showed that PD-L1+ FOXP3+ CD4+ (T-regulatory) cells coexisted with CD68+ and PD- L1+ CD68+ tumour-associated macrophages (TAMs) in the stroma of ARID1Amut low-risk patients." (PMID 37569458, 2023). "TNFR2 is highly expressed by the maximally immunosuppressive subset of CD4+Foxp3+ regulatory T cells (Tregs), especially those present in tumor microenvironment (TME)." (PMID 36865537, 2023). "These contradictory results have stemmed from an assessment of the prognostic impact of FOXP3 lymphocytes in different tumor tissues." (PMID 37960147, 2023). "In contrast, immunosuppressive tumor microenvironments are formed by M2 macrophages, forkhead box P3+ (Foxp3+) regulatory T lymphocytes (Tregs), and myeloid-derived suppressor cells (MDSCs)." (PMID 37835376, 2023). "The addition of α-CTLA−4mAb to RT and αCD40mAb therapy also resulted in a significant increase in the ratio of CD8+: Foxp3+ cells compared to RT and αCD40mAb group (p < 0.05) and to RT alone and control tumor samples (p < 0.001)." (PMID 37332616, 2023). "Although the role of Foxp3 in regulating immunosuppression is very well known, its actions in tumor cells remain uncertain." (PMID 37766222, 2023). "Studies show that FOXP3 expression by cancer cells results in the secretion of cytokines such as IL-10 and TGFβ into the tumor microenvironment, which suppresses immunity." (PMID 37176567, 2023). "mIHC results showed that Abrine co-treated with anti-PD-1 antibody increased CD8+ cytotoxic T cells infiltration in tumor cells, decreased Foxp3+ Treg cells, and inhibited IDO1 and PD-L1 expression." (PMID 37334368, 2023). "S15+ tumor cells or TAMs were spatially closer to CD4+FoxP3+ Tregs than S15− tumor cells or TAMs, both in the PD-L1− or PD-L1+ tumor cells or TAMs." (PMID 37674198, 2023). "When DKK1 was overexpressed in our Nicd/Akt model, we found a significant increase in FOXP3+ cells within tumour boundaries (p = .0076)." (PMID 35924447, 2023). "High TIL counts, both FoxP3 + and CD8 + mTILs, were associated with a higher histological tumor grade (p ≤ 0.007)." (PMID 37428418, 2023).
tumor (continued). "To further validate the correlation between RNASET2 and Tregs, we collected 12 ccRCC tumor samples for immunohistochemical staining analysis, and Foxp3 was used to label Tregs." (PMID 37679715, 2023). "It is becoming increasingly clear that tumor-derived factors play a role in recruiting and amplifying FoxP3+Tregs, and the presence of FoxP3+Tregs in these tumors blocks effective immunity to cancer." (PMID 36978120, 2023). "Three subjects had preinfusion and postinfusion tumor tissue analyzed for markers of immune activation (CD3, CD4, CD8), regulatory T cell function (Foxp3) and tumor cell proliferation (Ki67, pS6)." (PMID 37377890, 2023). "In our discovery cohort, we evaluated the expression profiles of CMTM6, PD-L1, CTLA-4, and FOXP3 in 177 HNSCCs from Caucasian patients of all tumor stages and different treatment regimens, correlating marker expression in tumor and immune cells with outcomes." (PMID 38067301, 2023). "FN infection was associated with T cell depletion and enrichment of exhausted CD8+ and FoxP3+ regulatory T cells in the tumor microenvironment." (PMID 36960042, 2023). "Although the expression of Foxp3 has been reported in many tumor cell types, the regulation of its expression has been barely explored." (PMID 37766222, 2023). "In this study, we found that propolis administration increased the density of CD3+ and CD4+ TILs and decreased the density of FOXP3 lymphocytes in the lamina propria of the tumor microenvironment in the mice with early stage CRC." (PMID 37960147, 2023). "Propolis potentially prevented CRC progression by increasing the levels of CD3+ and CD4+ TILs and reducing the levels of FOXP3 lymphocytes in the tumor microenvironment in early stage CRC." (PMID 37960147, 2023). "CD4+FoxP3+ Tregs were associated with a bad prognosis in the TME (P = 0.044), as well as CD4+FoxP3+ Tregs surrounding S15− tumor cells (P = 0.035), and S15+ tumor cells (P = 0.008)." (PMID 37674198, 2023). "Other authors have found CCL11 protein increases the proportion of CD4 + CD25 + Foxp3+ Treg cells, the expression of CCR3 and Foxp3, and the release of IL2 and TGFβ1 in non-tumour-associated CD4+ T cells via the STAT5 signalling pathway." (PMID 37626783, 2023). "Because CD4+CD25+ Treg cells are among the most prominent anti-tumor and pro-transplant cells, the regulation of their driving force transcription factor (FoxP3) is a potential site of therapeutic attack." (PMID 37296860, 2023). "The expansion of the effector/memory phenotype of FOXP3+Tregs13 with a similar transcriptional profile of tumor-infiltrated Tregs14 was previously detected during COVID-19." (PMID 37604833, 2023). "Foxp3 overexpression induces the viability and invasiveness of lung cancer cells, resulting in tumor cell growth." (PMID 36776832, 2023). "In inner tumor areas, FOXP3+ TILs and FOXP3/CD8 ratio were significantly higher in tumors invading the muscle (p = 0.04 and 0.02, respectively) in inner tumor areas." (PMID 36900270, 2023). "The prognostic value of FoxP3 expression is very controversial, depending on the site of expression (tumor cells or TILs) and the histopathological tumor type." (PMID 36980787, 2023). "However, Foxp3+ regulatory T-cells have low frequency in BC tissues, and their densities and localizations in a large series of patients with primary BC showed a significant association with higher tumor grade, HER2 positivity, ER negativity, and poor prognosis." (PMID 37835465, 2023). "There was a significant decrease in the number of Treg (CD25+Foxp3+ in CD4+) within the tumour in mice treated with Vacc DCs as compared to untreated mice." (PMID 37660049, 2023). "Subsequent studies evaluating FOXP3 isoforms and their effect on immune cells will provide a better understanding of the immunomodulatory effects of FOXP3 expression in tumor cells." (PMID 36672296, 2023). "Foxp3+CD4+CD25+CD127low/- T cells showed significantly positive correlation with AFP, associated with tumor size in HBV-HCC patients." (PMID 38090482, 2023).
tumor (continued). "In patient samples acquired prior to Neoadjuvant Chemotherapy (NAC), the presence of both IL-33 and FOXP3 proteins was confirmed, with IL-33 detected primarily in the stromal tumor lesion." (PMID 37762328, 2023). "In our study, we analyzed the FoxP3 transcriptome across TCGA cancers, and we found that the FoxP3 was highly expressed in the tumor tissues of ccRCC patients with BAP1- or SETD2-mutant genotype." (PMID 37569676, 2023). "In all groups, there was a significantly higher percentage of FoxP3+ B cells of the total B cell population in the tumor tissue compared to the adjacent tissue." (PMID 37587309, 2023). "More recent findings reveal a positive correlation between the overexpression of IL-33 and FOXP3 expression within the tumor microenvironment, suggesting that IL-33 contributes to immunosuppression." (PMID 37762328, 2023). "iTregs are generated by the conversion of peripheral naive T cells induced by transforming growth factor-β (TGF-β) or IFN-γ and negatively regulate anti-tumor immunity, with less stable Foxp3 expression." (PMID 37833255, 2023). "Accordingly, the overall CD8/FOXP3 ratio that we measured in the study correlates well with the tumour burden in both models." (PMID 38077324, 2023). "In all treatment groups, percentage of FoxP3+ B cells was significantly higher in tumor tissue compared to adjacent tissue." (PMID 37587309, 2023). "Overall, this analysis showed that tumor infiltrating CD4 + FoxP3 + T-cells co-expressed most of our ICPs of interest." (PMID 38057799, 2023). "A high level of FOXP3 expression was observed in tumor cells compared to tumor-surrounding tissues, as detected through an immunohistochemistry assay." (PMID 37176567, 2023). "A similar decrease in FoxP3+ cell count was also observed when the number of Foxp3+ cells was calculated per gram of tumor tissue." (PMID 37122749, 2023). "The results showed that the percentage of CCL19 + cells were positively correlated with the percentage of FOXP3 + cells in tumor tissues." (PMID 37208608, 2023). "Tregs are critical for tumor immunity, particularly through the expression of FOXP3, which has a significant inhibitory effect on the anti-tumor immune response." (PMID 37723510, 2023). "Both histological subtypes also showed a significant difference in the number of FOXP3 + TILs in the stroma compartment of the tumor periphery (p = 0.02)." (PMID 36562826, 2023). "In fact, Tregs function have been shown to be dependent on the active expression of Foxp3, thus conferring Tregs with the ability to play a central role during tumor progression." (PMID 38313431, 2023). "In a study of breast cancer cells, tumor infiltration by anti-tumor NKT cells and the expression of PD-L1, IDO1 and FoxP3 were associated with high levels of glycolysis, an observation partly attributed to the intermediate expression of IL-17." (PMID 37296860, 2023). "As previously noted, Foxp3 + Treg cells can limit effector T cells’ function as well as increase tumor immune evasion." (PMID 37658402, 2023). "PMN‐MDSCs inhibit TGF‐1‐induced differentiation of naïve T cells into Foxp3‐expressing iTregs in tumor‐bearing mice via ROS and IDO, and this occurs early in the differentiation process." (PMID 37382257, 2023). "Other inhibitory cell populations of the tumor immune microenvironment include, for example, FOXP3 + regulatory T cells (Tregs)." (PMID 36562826, 2023). "Tumor-promoting CD4+CD25+FOXP3+ T-regulatory cells (Tregs) have been described to abolish host defense mechanisms by impeding the activities of other immune cells including effector T cells." (PMID 38038865, 2023). "These clusters had a variable expression of FoxP3, and several were mainly, or only, present in tumor and lymph node tissue." (PMID 37232845, 2023). "We also found that the patients in the FoxP3 high-expression group had more Tregs infiltration in the tumor microenvironment." (PMID 37569676, 2023).
tumor (continued). "Targeting USP44 can reduce FOXP3 expression at the protein level, and thus break immune tolerance in tumor patients." (PMID 37053008, 2023). "Although the tumor CD8+:FoxP3+ ratio increased in six of nine pairs of biopsies, the difference was not statistically significant." (PMID 38115208, 2023). "Down-regulation of PD-L1 and TGF-β1 and FOXP3 up-regulation suggested that MTE inhibits the immune escape of tumor cells and Treg differentiation." (PMID 37649480, 2023). "The connection was firstly validated between chemokine receptor 4 (CCR4), a tumor-specific chemokine receptor, and FOXP3, shedding light on HAT1′s implication in BC." (PMID 37048148, 2023). "The increased presence of FOXP3 Tregs and CD68 macrophages have been linked to poor survival and tumor growth in NPC via NF-κB pathway alterations." (PMID 37046826, 2023). "In this context, an increased proportion of Foxp3+ regulatory T cells (Tregs) in LNs is expected to contribute to the suppression of anti-tumor immunity." (PMID 38067325, 2023). "FoxP3 regulatory T cells are an immunosuppressive subpopulation of CD4+ T cells that modulate the anti-tumor response mediated by CD8+ T cells." (PMID 37104271, 2023). "Certain SCLC tumor cell lines induce de novo differentiation of functional FOXP3+ Tregs in healthy blood lymphocytes." (PMID 37206058, 2023). "High percentage of protein tyrosine phosphatase receptor-type C+ (PTPRC+) cells in cervical tumor are associated with enhanced tumor-infiltration by T-BET+ cells and FOXP3+ cells." (PMID 36905477, 2023). "Our scRNA-seq analysis identified six subpopulations of Tregs, with varying expression of FoxP3 across the cells isolated from tumor, lymph node and blood compartments." (PMID 37232845, 2023). "In this way, the significance of FoxP3+ Tregs is depends on the biological properties of specific tumor type, stage and molecular subtype." (PMID 38313431, 2023). "Regulatory T cells (Treg) are a subclass of CD4+ cells that specifically express Forkhead box protein 3 (Foxp3) and are critical in regulating the anti-tumor response of T cells in the tumor microenvironment." (PMID 36831655, 2023). "In our study, patients in the sCRC group with high levels of FOXP3+ cells had earlier tumor stages than those with low levels." (PMID 37835436, 2023). "F. nucleatum-enriched subset of MSI-high CRCs had decreased forkhead box P3 (FoxP3)+ T cells at both invasive margin and center of tumor areas." (PMID 37868956, 2023). "FoxP3, a sign of Treg activity, has been proposed as a marker of tumor progression and metastasis in breast carcinoma." (PMID 37056346, 2023). "They constructed an immune scoring system based on the density of interstitial CD8+ TILs, interstitial Foxp3+ TILs, tumor area Foxp3+ TILs, and tumor area PD-1+ TILs, which showed correlations with patient LRFS and OS." (PMID 37720221, 2023). "FoxP3+ Tregs in the tumor impede effective anti-cancer immune responses and diminish the effect of PD-1/PD-L1 monoclonal antibodies; in contrast, Th17 cells in this context act as promoters of tumor growth." (PMID 37869003, 2023). "It has been exhibited that the inhibition of adenosine A2A receptor in tongue SCC is associated with the activation of CD8 + T lymphocytes and a reduction in the number of Foxp3 + Tregs, leading to tumor repression." (PMID 37221555, 2023). "Although a few studies have investigated the role of glycosylation in Tregs and Foxp3 regulation, the potential of O-GlcNAcylation targeted therapy in modulating the function of Tregs should be investigated to achieve anti-tumor and anti-autoimmune immunity." (PMID 37936703, 2023).